IL13 (interleukin 13)
Diseases named in the same sentence as IL13 in open-access papers (continued):
Sharing a sentence is not in itself a finding about the gene and the disease.
inflammation (continued). "Intratracheal suppression of SUMOylation by 2-D08 robustly attenuates not only allergen-induced airway inflammation, goblet cell metaplasia, and hyperreactivity, but IL-13-induced goblet cell metaplasia." (PMID 37393345, 2023). "IL-13 induces Arachidonic Acid 15-Lipoxygenase (ALOX15) expression, an enzyme oxidizing polyunsaturated fatty acids, and causes eosinophil-mediated airway inflammation." (PMID 35887565, 2022). "In fact, IL-13 released by Tregs induces IL-10 secretion in IL13R+ macrophages in models of acute systemic inflammation." (PMID 36140212, 2022). "Previous studies have indicated that IL‐13/IL‐4Rα signalling pathway is involved in the amplification and polarization of the alveolar and bone marrow–derived macrophages, resulting in airway inflammation." (PMID 33305406, 2021). "Consistent with our results, ILC2s are also the major source of IL-13 in the lungs of mice undergoing acute airway inflammation induced by papain, house dust mite, or ovalbumin." (PMID 32179159, 2020). "The type I hypersensitivity reaction, one of the main pathological mechanisms in AR, is characterized by eosinophilic inflammation accompanied by increases in type 2 cytokines, such as IL-4, IL-5, and IL-13, in affected tissues and blood." (PMID 32824013, 2020). "Some literatures show that LYN in allergic airway inflammation can reduce inflammatory cell infiltration and levels of IL-13 and IL-4 and downregulate allergen-induced airway inflammation." (PMID 33215029, 2020). "For the investigation of the expression of downstream cytokines related to the IL-33/ST2 receptor signaling axis, IL-13 is mainly secreted after IL-33 stimulation and can induce epithelial injury and biliary inflammation." (PMID 31632941, 2019). "We found that the chronic eosinophilic sinonasal inflammation and type 2 immune response, including the production of IL-4, IL-5, IL-13, and CCL11, were less severe in Ifnar1−/− mice than in the WT mice." (PMID 30455684, 2018). "IL-4, IL-10 and IL-13, as the classic anti-inflammatory cytokines, can decrease the production of inflammatory cytokines, and thus inhibit synovial inflammation and bone damage." (PMID 28056922, 2017). "Published studies have demonstrated that the TH2 production of the cytokine IL-13, in response to stimulation with IL-33, can promote the hyperplasia of epithelial cells in the context of airway inflammation." (PMID 28931041, 2017). "6, 7, 8, 9, 11, 12, 34, 35, the IL-5 and IL-13 cytokines produced by activated ILC2s are essential for eosinophilic inflammation and AHR development." (PMID 27752043, 2016). "Previous reports demonstrated that the levels of pro-inflammatory cytokines, IL-4, IL-5, and IL-13, and airway inflammation were suppressed in mice pre-treated with SCGB1A1 or SCGB3A2 in the OVA-induced allergic airway inflammation model." (PMID 26559674, 2015). "AAD treatment effectively decreased OVA-induced AHR, eosinophilic airway inflammation, and airway remodeling, which probably through decreased expression of IL-13 and TGF-β1." (PMID 24367979, 2013). "IL-13 is one of the main regulators of allergic inflammation and the key inducer of several type-2 cytokine-dependent pathologies." (PMID 23042234, 2013). "A decrease in the abundance of CD11c+ cells in the airways is typically seen in airway inflammation, induced for example with lipopolysaccharide, antigen, recombinant IL-13 or Interferon gamma." (PMID 22110701, 2011). "We therefore utilized a previously reported acute model of ovalbumin induced lung inflammation to study the effects of H4R antagonism and IL-13 on AHR." (PMID 20573261, 2010). "In addition, EVs from hypoxia-conditioned MSCs have been reported to suppress IL-4 and IL-13-driven airway inflammation through the delivery of anti-inflammatory molecular cargo, including miR-146a-5p." (PMID 41465563, 2025). "Interleukin-13 (IL-13), along with IL-4, is a key mediator of Th2-driven airway inflammation." (PMID 41002723, 2025).
inflammation (continued). "This epithelial injury triggers the release of alarmins IL-33 and TSLP, activates innate lymphoid cell types 2 (ILC2) and T cells, and promotes IL-5/IL-13-driven eosinophilic and interleukin-17A-mediated neutrophilic inflammation—resulting in mixed airway inflammation." (PMID 41450494, 2025). "In our previous study, we reported that IL-13 increased in the small intestinal mucosa in radiation-induced small intestinal inflammation and could contribute to mucosal injury." (PMID 37834420, 2023). "Early life hyperoxia exposure enhances innate lymphoid cell (ILC2) function by increasing the expression of IL-33, and ILC2s produce type 2 cytokines such as IL-5, IL-13, and mediators involved in tissue repair, leading to eosinophilic airway inflammation and airway remodeling." (PMID 37485534, 2023). "Although we observed a significant role of DPP4 in IL-13-induced airway eosinophilic inflammation, the contribution of DPP4 to airway eosinophilic inflammation mediated by IL-13 and PA remains unclear." (PMID 37287831, 2023). "An experimental model showed that reducing central cytokines IL-4 and IL-13 could control gut inflammation through the type 2 proinflammatory pathway of the gut mucosa." (PMID 36101343, 2022). "IL-13, the main mediator of allergic inflammation, is expressed in both acute and chronic AD." (PMID 34371956, 2021). "In addition, IL-10−/− mice with experimentally induced airway inflammation showed an increase in IL-13 production." (PMID 32778925, 2020). "GM-CSF and IL-6 can promote the activation and maturation of dendritic cells, macrophages, and T cells, providing an additional mechanism by which lung-expressed LIGHT together with IL-13 could perpetuate lung inflammation." (PMID 29616048, 2018). "Therefore, the positive correlation among IL-25, IL-5 and IL-13 indicates that IL-25 plays a role in the increase of Th2-type cytokines (IL-5 and IL-13) that induces asthmatic airway inflammation and promotes Th2-type adaptive immune responses." (PMID 27617447, 2016). "Along with the reduced eosinophilic airway inflammation, IL-13 levels in BALF tended to be lower in OLA-pretreated mice and the production of IL-4 and IL-5 was significantly reduced in BP-restimulated lung cells of OLA-pretreated mice compared to sensitised controls." (PMID 27149118, 2016). "Because TNF, IL-6, and IL-13 are expressed by various leukocytes, we decided to investigate whether eosinophil-specific products could also drive chronic intestinal inflammation." (PMID 26200014, 2015). "Also, the IL‐13/IL‐4Rα signalling pathway is involved in the amplification and polarization of the alveolar and bone marrow–derived macrophages, thus promoting the development of airway inflammation." (PMID 33305406, 2021). "Importantly, both IL-33 and IL-25 could activate ILC2, leading to production of IL-5 and IL-13, which mediates lung inflammation." (PMID 34970267, 2021). "In summary, the current study demonstrated that a traditional Chinese medication Suhuang could effectively decrease OVA-induced AHR, eosinophilic airway inflammation, mucus overproduction and airway remodeling, most likely through down-regulation of IL-13 and TGF-β1." (PMID 26861679, 2016). "In addition, the production of IL-13/IL-5 promoted by nuocytes induced airway inflammation." (PMID 27617447, 2016). "It has also been suggested that esophageal eosinophilic inflammation is mechanistically linked with pulmonary inflammation; this latter theory is based on the finding that repeated delivery of specific allergens or the TH2 cytokine IL-13 to the lung of mice induces experimental EE." (PMID 22792476, 2012). "We evaluated the gene-based expression of type 2 cytokines (IL-4, IL-5, and IL-13) and STAT 6, which is a transcription factor that plays a crucial role in the pathogenesis of allergen-induced airway inflammation." (PMID 38790633, 2024).
inflammation (continued). "The development of breads fermented with S. cerevisiae UFMG A-905 partially reduced airway inflammation, as demonstrated by the reduction in eosinophils and IL5 and IL13 concentrations." (PMID 38655128, 2024). "S. cerevisiae UFMG A-905–fermented breads partially reduced airway inflammation, decreasing eosinophils and IL5 and IL13 concentrations." (PMID 38655128, 2024). "Similarly, in our animal model, IL13 could be the inducing factor of colonic inflammation." (PMID 37893107, 2023). "IL-13 is also produced by innate lymphoid cells (nuocytes, ILC2s), which express MHC class II and help shape T cell responses that control airway inflammation." (PMID 29854835, 2018). "Conversely, it was rather unexpected that in HDM-induced allergic inflammation; which is Th2-driven, IL-13 was unnecessary for the induction of BRP-39; in other words BRP-39 induction was unaltered and yet eosinophilic inflammation was markedly attenuated." (PMID 21473774, 2011). "In fact, transfer of primed CD4+ T cells constitutively expressing SOCS-5 along with eye drop challenges in a murine allergic conjunctivitis model resulted in attenuated eosinophilic inflammation with enhanced IFN-γ and decreased IL-13 production." (PMID 18315837, 2008). "In vivo, it was found that ILC2 is the main source of IL-13 in lung inflammation, and this response does not depend on T cells." (PMID 33514798, 2021). "Improve lung inflammation by inhibiting the excessive recruitment of M1 and M2 under TGF-β1 to achieve a therapeutic effect, reducing the levels of MCP-1, TNF-α, IL-1β, IL-6, IL-10,IL-13, and OSM." (PMID 34489700, 2021). "IL-13, IL-1R1, IL-18, and BRP-39 knock out (KO) mice were utilized to assess the mechanism and relevance of BRP-39 in cigarette smoke- and HDM-induced airway inflammation." (PMID 21473774, 2011). "In addition, we constructed an immune inflammation-related PPIN (confidence level >0.4) involving interleukin-4 and interleukin-13 signaling, interleukin-10 signaling, and arachidonic acid metabolism, and calculated the degree, betweenness and closeness of each node in the network." (PMID 36003498, 2022). "Besides, the correlations between BIRC3 expression and asthmatic eosinophilic/allergic inflammation indicators (FeNO, IgE, and EOS%), pulmonary function (FEV1, FEV1% pred, FVC% pred, and FEV1/FVC), and inflammatory cytokines (IL-4, IL-5, IL-13, IL-25, IL-10, IL-33, and TSLP) were analyzed." (PMID 35287655, 2022). "Systemic inflammation in obese boys was characterized by higher expression of TNF-β (p = 0.011), IL-15 (p = 0.004), and IL-2 (p = 0.046) and significantly lower concentrations of anti-inflammatory cytokines such as IL-10 (p = 0.035) and IL-13 (p = 0.002), compared to eutrophic males." (PMID 33526854, 2021). "However, Soy3+DEP promotes AHR and both neutrophilic and eosinophilic pulmonary inflammation, without increasing the levels of IgE, and more importantly without the involvement of IL-4 and IL-13." (PMID 28628664, 2017). "It is known that IL-13 is involved in lung goblet cell hyperplasia and mucus hypersecretion, while IFN-γ inhibited IL-13-induced goblet cell hyperplasia in a mouse model of airway inflammation and it is a potent inhibitor of mucin secretion in a human colonic goblet cell line." (PMID 24453426, 2013). "Transfer of WT pDCs also limited RV-induced AHR, eosinophilic airways inflammation and production of IL-5 and CCL11 but not IL-13 release." (PMID 26108570, 2015).
respiratory disease (22 papers, 2011 to 2025). "The induction of CD4+ type 2 helper T-cell (Th2) (IL4, IL5, or IL13) responses has been associated with vaccine-associated enhanced respiratory disease (VAERD), as seen in some patients with respiratory virus infections." (PMID 36685587, 2022). "Previously, Th2 biased responses orchestrated by IL-13 were usually associated with vaccine-associated enhanced respiratory disease (VAERD)." (PMID 33562141, 2021). "However, the induction of TH2 cytokines such as IL-4, IL-5 and IL-13 has been associated with vaccine-associated enhanced respiratory disease (VAERD), a set of diseases with predominant involvement of the lower respiratory tract." (PMID 35287350, 2022). "Increasing studies have revealed that IL-13 is an important mediator in multiple infectious and respiratory diseases, such as excessive inflammation, polarization of M2 macrophages, immune evasion of virus, pulmonary fibrosis, and viral pneumonia." (PMID 38508309, 2024). "Five individual mediators were different among the cohorts (MCP‐1, IL‐7, IL‐10, IL‐13, and IL‐15) with lower concentrations in the groups with respiratory disease, particularly COPD and CRS." (PMID 36780897, 2023). "The Th1/Th2 balance has been recognized as an important factor among vaccine researchers because vaccine-associated enhanced respiratory disease (VAERD) is largely associated with low-titer neutralizing antibodies and Th2-biased immune responses (related to IL-4 and IL-13 cytokines)." (PMID 35632468, 2022). "Levels of IL-4, IL-5, IL-13, and eotaxin followed the pattern established in the previous study and correlated inversely with antibody levels and directly with pulmonary eosinophilia as previously reported for other respiratory diseases." (PMID 36560488, 2022). "Understanding the relationship between IL-13 and HA may be widely relevant to respiratory diseases beyond COVID-19." (PMID 34185704, 2021). "As IL-13 is well-known, to induce respiratory disease, the decrease of the IL-13 concentration in the lung homogenate in group 3 mice might represent an additional mechanistic aspect of the regenerative effects of Treamid." (PMID 33171668, 2020). "Therefore, understanding the roles of IL-6, IL-13, IFN-γ, and TNF-α is essential for developing an effective vaccine and treatment against SARS-CoV-2 and other respiratory diseases." (PMID 38060612, 2023).
immune dysfunction (21 papers, 2012 to 2025). "Imbalances in IL-4, IL-10 and IL-13 levels can cause immune dysfunction, causing APOs." (PMID 41394354, 2025). "Preparations from Hericium coralloides and T. versicolor rebalanced cytokine profiles in immune cells from older adults, reducing IL-5 and IL-13 while adjusting IL-1β, IL-6, and interferon levels—an effect relevant to age-related immune dysfunction." (PMID 41488566, 2025). "It is possible that the balance between Th1/Th2 cells changes with the progression of immune disorders in pSS, and IL13 plays a potentially crucial local role in regulating glandular function." (PMID 36143051, 2022). "GATA-3 upregulation in CD8+ T cells has been identified as a biomarker of immune dysfunction in SSc, resulting in excessive IL-13 production." (PMID 36232733, 2022). "Among 42 cytokines measured, significant changes were observed for only 4 cytokines (IL-13, IL-17, IL-26, MIP-1β), three of which were reported as overexpressed in auto-immune diseases (IL-17, IL-13, IL-26)." (PMID 32429322, 2020). "It has been shown that autophagy is essential for airway mucus secretion in a type 2, IL-13-dependent immune disease process and the regulation of autophagy by Th2 cytokines is cell-context dependent." (PMID 30651971, 2019). "CD is characterized as a Th1-mediated inflammatory response with overproduction of interferon-γ (IFN-γ) and TNF-α whereas UC is considered a Th2-mediated immune disease with massive production of interleukin IL-4, IL-5, IL-9, and IL-13." (PMID 30150894, 2018). "The increases in the proinflammatory cytokines IL-1a, IL-8, IL-17A, IL-12p40, TNF-β, MCP-1, IL-2, and IL-12p70 and the anti-inflammatory cytokines IL-10 and IL-13 observed in AD patients in our study are consistent with prior evidence of immune dysfunction in AD." (PMID 39346576, 2024). "Additionally, multiplex cytokine analysis revealed significant elevations in Eotaxin, IL-1β, IL-4, IL-6, IL-8, MIP-1α, and TNF-α in SZ patients, whereas IFN-γ, IL-9, IL-1ra, IL-13, MCP-1, MIP-1β, and RANTES were reduced (p < 0.05), indicating a complex immune dysfunction associated with SZ." (PMID 40761785, 2025). "In the current study, upregulation of c-Maf, GATA3, IL-5, and IL-13 in the colonic mucosa of HES goats confirmed that the colonic inflammation in growing goats caused by HES was attributed to the TH2 cytokine pattern, which might be related to the TH2-mediated immune disorder." (PMID 38395946, 2024). "It is well known that IFN-γ, IL-4/IL-5/IL-13 and IL-17 are pro-inflammatory cytokines expressed or secreted by activated Th1, Th2 and TH17 cells, respectively, and play key roles in various immune diseases." (PMID 38664707, 2024).
bacterial infections (17 papers, 2013 to 2025). "One point that deserves further discussion is that most bacterial infections cause a type I immune response, whereas the type II cytokine, IL-13, was overexpressed in our model." (PMID 34858903, 2021). "We then scored the association between BPIFA1 and IL-13 expression levels in patients with bacterial infection." (PMID 26646664, 2015). "However, the molecular mechanisms underlying IL-13 perturbation of bacterial infection and BPIFA1 expression in host airways require further exploration." (PMID 26646664, 2015). "Although this study has established a cell-based model to demonstrate that IL-13 suppresses BPIFA1 expression in CRSwNP patients with bacterial infections, some limitations are evident." (PMID 26646664, 2015). "In contrast, there were 3, 2, 1, and 0 patients showing IL-13 staining of grades 0, 1, 2, and 3, respectively, in the CRSwNP group with bacterial infection." (PMID 26646664, 2015). "Additionally, it is also noteworthy that HPV infection modulates the immunological response towards a predominance of Th2-type response (IL-4, IL-5, IL-10, and IL-13), which favors persistence of bacterial infection." (PMID 36897879, 2023). "Moreover, the immunohistochemical analysis showed that IL-13 prominently suppressed BPIFA1 expression in eosinophilic CRSwNP patients with bacterial infection." (PMID 26646664, 2015). "However, the molecular mechanism of IL-13 perturbation of bacterial infection and BPIFA1 expression in host airways remains unclear." (PMID 26646664, 2015). "However, high circulating levels of allergy pathway cytokines (IL-13, IL-4), a prominent feature in severe SARS-CoV-2 infection, are uncommon in most bacterial infections." (PMID 37040185, 2023). "In addition, MC degranulated and produced ROS, TNF-α, IL-1β, IL-6, IL-13 and MCP-1 in response to bacterial infection." (PMID 34194428, 2021). "Especially in the absence of bacterial infection, eosinophilic inflammation is a fairly good and specific surrogate for high IL-13 levels." (PMID 31262043, 2019). "Conversely, the level of BPIFA1 expression was markedly reduced in tissues with bacterial infection and expressing a high level of IL-13 as compared to that in tissues without IL-13 expression." (PMID 26646664, 2015). "Therefore, further investigation is required to clarify the link between IL-13 production and BPIFA1 expression in other types of CRSwNP patients with bacterial infections to provide an opportunity to develop novel strategies to improve therapeutic outcomes." (PMID 26646664, 2015). "In this study, we showed that IL-13 suppresses BPIFA1 secretion from nasal epithelium; hence, it may reduce the innate immune response countering the bacterial infection." (PMID 26646664, 2015). "All CRSwNP patients without bacterial infection showed neither BPIFA1 nor IL-13 expression." (PMID 26646664, 2015).